ABCG2 (ATP binding cassette subfamily G member 2 (JR blood group))
Diseases named in the same sentence as ABCG2 in open-access papers (continued):
Sharing a sentence is not in itself a finding about the gene and the disease.
ovarian carcinoma (continued). "A side population of cells expressing NANOG, OCT4 and ABCG2/BCRP1 was isolated from ovarian cancer cell lines and ascites of ovarian cancer patients, and was found to have increased tumourgenicity and chemoresistance." (PMID 34283069, 2021). "ABCG2 is a marker of ovarian cancer stem cells and highly expressed in ovarian cancer spheroids which have higher chemoresistance to cisplatin or paclitaxel." (PMID 35582032, 2021). "Downregulation of miR-411, mediated by low levels of SLC27A2, enhances the expression of ABCG2, which promotes drug efflux to induce cisplatin resistance in ovarian cancer." (PMID 34660304, 2021). "The inhibition of Gli1 expression decreases ABCB1 and ABCG2 gene expression levels, thus enhancing the response of ovarian cancer cells to certain chemotherapeutic drugs." (PMID 33968932, 2021). "Here, we report the novel finding that the ATP-binding cassette (ABC) transporter ABCG2 contributes to MLN4924 drug resistance in A2780/MLN-R ovarian cancer cells and other cell models where ABCG2 is overexpressed." (PMID 32059437, 2020). "In our study, the c-Kit-mediated upregulation of cancer stemness-related Notch3—PBX1 and β-catenin—ABCG2 signaling pathways and promotion of ovarian cancer tumorigenicity and drug resistance were all phospho-PHBY259 dependent." (PMID 32169072, 2020). "In agreement with our ovarian cancer data, the ABCG2-overexpressing NCI-H460/MX20 cells were significantly less sensitive to MLN4924." (PMID 32059437, 2020). "It has been reported that c-Kit regulates the chemoresistance and tumor-initiating capacity of ovarian cancer cells through the β-catenin—ABCG2 pathway." (PMID 32169072, 2020). "Serial sections of paraffin-embedded serous-type ovarian cancer lesions were used to detect ABCG2 and SIK3 protein levels by immunohistochemistry." (PMID 31762812, 2019). "Expression of ABCB1 and ABCG2 correlates with resistance to cisplatin and paclitaxel in ovarian cancer cell lines (2008, KF28, TU-OM-1, OVCAR3, SKOV3) and in cells from patient and mouse ascites." (PMID 30042330, 2018). "In ovarian cancer, expression of ATP-binding cassette transporter (ABC transporter) proteins including ABCG2 and MDR1 are closely related with drug resistance." (PMID 30526541, 2018). "The ABC transporter protein ABCG2/BCRP1 has alsobeen shown to have a high expression in ovarian cancer cells found within theascites." (PMID 31069311, 2018). "Inhibition of Gli1 decreases ABCB1 and ABCG2 gene expression in ovarian cancer and enhances ovarian cancer-specific chemotherapeutic response." (PMID 29117122, 2017). "Knockdown of SOX2 expression with shRNA in primary ovarian cancer spheres resulted in significantly decreased sphere forming activity and ABCG2 expression." (PMID 27489349, 2016). "Recent studies have found the involvement of the Wnt/β-catenin-ABCG2 signaling pathway in chemoresistance and tumor-initiating capacity of ovarian cancer cells." (PMID 27229859, 2016). "It was recently found that abnormal expression of the hedgehog (Hh) signaling pathway transcription factor Gli1 is involved in the regulation of ABC transporters ABCB1 and ABCG2 in ovarian cancer." (PMID 26649310, 2015). "It was found that the inhibition of Gli1 expression can decrease ABCB1 and ABCG2 gene expression levels and enhance the response of ovarian cancer cells to specific chemotherapeutics." (PMID 26649310, 2015). "AuNPs inhibit cisplatin induced EMT, decrease the side population cells and key stem cell markers such as ALDH1, CD44, CD133, Sox2, MDR1 and ABCG2 in ovarian cancer cells." (PMID 25071019, 2014). "Our previous studies have demonstrated that the ovarian cancer cell lines of SKOV-3 and A2780 expressed transporters of ABCG2 and ABCB1 that were closely associated with the drug resistance." (PMID 23368632, 2013). "ABCG2/BCRP1 expression was also found in human ovarian cancer cells from patient ascites and was expressed in SP cells more extensively than in non-SP cells." (PMID 20354527, 2010).
ovarian carcinoma (continued). "For instance, hypermethylation of ABCB1 and demethylation of the ABCG2 promoter may affect therapeutic efficacy and lead to chemoresistance in ovarian carcinoma, effects attributed to upregulation of P-gp." (PMID 38539161, 2024). "Similarly, for iron export, lower expression levels of ABCG2, FLVCR1, and FLVCR2 were associated with an advanced stage of ovarian cancer." (PMID 38186569, 2023). "Likewise, Hedgehog signaling directly regulates the expression of ABCB1 and ABCG2 in ovarian cancer." (PMID 33968932, 2021). "However, a significant overexpression of ABCG2 mRNA and protein was observed in topotecan-resistant ovarian cancer cell lines." (PMID 35582032, 2021). "Therefore, more studies on the miRNA-induced ABCB1 or ABCG2 expression, which leads to drug resistance in ovarian cancer, will improve our understanding of the drug resistance mechanism of ABC transporters." (PMID 34660304, 2021). "In summary, we have shown that the association of c-Kit with PHB upregulated phospho-PHBY259 in the lipid raft domain, resulting in subsequent activation of the Notch3—PBX1 and β-catenin—ABCG2 signaling pathways to increase stemness, tumorigenicity and drug resistance in ovarian cancer." (PMID 32169072, 2020). "From our in vitro studies, we found that the ovarian cancer cell lines SKOV3 and OVCAR4 with SIK3 knockdown displayed significant chemoresistance to Taxol/cisplatin, which was specifically associated with the upregulation of ABCG2." (PMID 31762812, 2019). "Consistent with previous study, our data reveal that cholesterol alone and malignant ascites derived from ovarian cancer patients upregulates the protein expression of ABCG2 and MDR1, associated with poor prognosis and chemoresistance in ovarian cancer patients." (PMID 30526541, 2018). "Finally, ABCC11 and ABCG2 have also been detected in ovarian cancers; the ABCG2 as a marker of side-populations of ovarian cancer cells that show stem-cell characteristics." (PMID 28674494, 2017). "Since the application of wall shear stress increases the expression of ABCG2 and P-gp, we hypothesized that ascitic flow can enhance the chemoresistance of ovarian cancer spheroids." (PMID 27245437, 2016). "Moreover, OVCAR-5 CXCR4+CD133+ cells migrated toward the CXCR4 ligand CXCL12, were less sensitive to the most popular chemotherapeutic agent utilized in ovarian cancer, cisplatin, and over expressed the drug resistance transporter ABCG2." (PMID 26020117, 2015). "c-Kit was suggested to activate ABCG2 drug transporters to confer chemoresistance in ovarian cancer which might explain why stem cells are resistant to a variety of agents, rather than to one single chemotherapeutic agent." (PMID 24009080, 2013). "The c‐KIT/phospho‐PHB axis has been reported to increase ovarian cancer stemness and chemoresistance via Notch3–PBX1 and β‐catenin–ABCG2 signaling." (PMID 41179704, 2025). "Ursolic acid diminishes ABCG2 expression and reverses cisplatin tolerance via blockage of PI3K/Akt pathway mediated activation of HIF-1α in ovarian cancer stem cells." (PMID 40612109, 2025). "In our previous study, we checked the expression of ovarian cancer stemness markers ALDH, CD44, ABCG2, and NANOG and spheroids’ clonogenic nature through PKH staining." (PMID 39596687, 2024). "FOXP1 functions as an oncogene in epithelial ovarian cancer cells by promoting the CSC-like characteristics, while its overexpression led to an up-regulated expression of ABCG2, OCT4, NANOG, and SOX2 genes and protected cells against apoptotic cell death." (PMID 37189618, 2023). "Firstly, we analyzed the expression of known ovarian cancer stemness markers: ALDH1, CD44, ABCG2, and NANOG." (PMID 37511212, 2023). "Based on these results, it was revealed that in ascites-derived human ovarian cancer cells, ABCC1 and ABCG2 promote drug efflux." (PMID 36551731, 2022).
ovarian carcinoma (continued). "ABCG2 promoter hypomethylation has been observed in MDR cell line models of ALL leukemia, ovarian carcinoma, and a stem-like cell subpopulation of prostate carcinoma." (PMID 33066132, 2020). "In our study, ovarian cancer cells with SIK3 knockdown and ABCG2 upregulation showed significant chemoresistance to Taxol/cisplatin treatment." (PMID 31762812, 2019). "Treatment of human ovarian carcinoma A2780RCIS (ABCC2) and human gastric carcinoma EPG85-257RNOV (ABCG2) cell lines with this construct inhibited expression of the targeted encoding mRNA and protein itself." (PMID 29401721, 2018). "In ovarian cancer cells isolated for the SP, Notch pathway genes (FPTG, ST3GAL6, and ADAM19), stem cell markers NANOG and OCT4, and three ABC transporter genes (ABCG2 [both lines], ABCC4 [SKOV3 only], and ABCB1 [A224 only]) were induced." (PMID 30042330, 2018). "In the present study, we found that ABCG2, MDR1 and LXRα/β protein expression levels were correlated with resistance to CDDP and PAC in three ovarian cancer cells." (PMID 30526541, 2018). "Previously, we also observed increased expression of ABCG2 gene, after a short time of exposure to TOP, in ovarian cancer cell lines." (PMID 29027969, 2017). "In both, the cervix cancer cell line KB-3-1 and the ovarian carcinoma cell line A2780, the ABCB1 promoter was found to be highly methylated, whereas the ABCG2 promoter was unmethylated." (PMID 27689338, 2016). "Hypomethylation of the ABCG2 promoter has for example been found in ABCG2-overexpressing sublines of MCF-7, CCRF-CEM, IGROV1 (ovarian carcinoma) and A549 (non-small cell lung cancer) cells." (PMID 27689338, 2016). "In the current study, we showed FOXP1 up-regulated transcription activity of ABCG2, OCT4, NANOG, and SOX2 in A2780 ovarian cancer cells." (PMID 26654944, 2016). "We here show for the first time equivalence of ABCG2- and ABCB1-expressing ovarian cancer SP cells regarding stem cell properties such as clonogenicity, tumorigenicity, and asymmetric division." (PMID 25216521, 2014). "Dual positive (ABCG2-positive and ALDH1-positive) ovarian cancer cells were detectable in ovarian carcinoma tissue." (PMID 23967051, 2013). "Our study shows that ovarian cancer SP cells express the embryonic stem cell markers, NANOG, OCT4, STELLAR, and ABCG2/BCRP1." (PMID 20354527, 2010). "Interestingly, AhRR and PPP1R3C expression significantly correlates with stemness markers’ (ALDH1A1, CD44, ABCG2, NANOG) expressions in ovarian cancer tissues (p < 0.01)." (PMID 37511212, 2023). "Similarly, most genes involved in iron export, such as SLC40A1, FLVCR1, ABCG2, and MON1A, displayed reduced expression in ovarian cancer tissues; in contrast, only one gene, FLVCR2, showed the opposite trend." (PMID 38186569, 2023). "In order to scrutinize the initiating cell status and identity of iOVCAR-3-OSKM cells, we evaluated the expression levels of several ovarian cancer initiating cell (OCIC) markers that previously reported like CD133, CD177, CD24, CD44, ABCG2, and ALDH1 in cells." (PMID 36085021, 2022). "In addition to ABCG2/BCRP1, many embryonic stem cell markers, such as NANOG, OCT4 and STELLAR, were expressed in SP cells of ovarian cancer." (PMID 35982417, 2022). "Expression of stem cell markers (OCT4, SOX2, NANOG, NESTIN, ABCG2, CD133 and CD117) in ovarian cancer (sphere cells) represent their tumorigenic potential, and resistance to cisplatin, paclitaxel, adriamycin and methotrexate, which highlights the significance of “stemness” of cancer cells." (PMID 30121075, 2018). "In agreement with the situation in research on other solid tumors (e.g., ovarian cancer), it may be concluded that single genes and protein products as ABCB1, ABCC1, and ABCG2 connected with chemoresistance are well characterized also in EC." (PMID 29543757, 2018).
ovarian carcinoma (continued). "Here we show that cholesterol is elevated in malignant ascites and modulates the sensitivity of ovarian cancer cells to CDDP and PAC by upregulating the expression of drug efflux pump proteins, ABCG2 and MDR1, together with upregulation of LXRɑ/β, the cholesterol receptor." (PMID 30526541, 2018). "Though broader spectrum of CSCs may need to be tested to evaluate how common FOXP1 to core CSC transcription network, FOXP1 up-regulates expression of CSC-related core transcription factors, including ABCG2, OCT4, NANOG, and SOX2, in ovarian cancer cells." (PMID 26654944, 2016). "In addition to activating EMT, β-catenin directly regulates the transcription of ATP-binding cassette (ABC) transporter genes such as ABCG2/BCRP and ABCB1/MDR1 in ovarian cancer." (PMID 27776341, 2016). "For instance, ABCB1-expressing, but not ABCG2-positive, SP cells will be resistant to paclitaxel, an agent commonly used for ovarian cancer treatment." (PMID 25216521, 2014). "However, we did not observe a significant relationship between ABCG2 expression and acquired chemoresistance, which is in agreement with another study that did not observe any difference in ABCG2 expression in A2780 ovarian cancer cell treated with cisplatin." (PMID 35582032, 2021). "Verapamil, an ABC transporter inhibitor, which does not significantly inhibit the MDRI transporter, blocked SP cells from excluding the Hoechst dye, indicating the important role of ABCG2/BRCP1 in the SP of ovarian cancer cells." (PMID 20354527, 2010). "Stem cell markers NANOG and ABCG2/BCRP1 were colocalised in both SP and non-SP cells, and the specific individual cells in ovarian cancer tissues, as illustrated in our study, make it reasonable to hypothesise that there are cancer stem-like cell niches in ovarian cancer." (PMID 20354527, 2010).
leukemia (88 papers, 2007 to 2026). A malignant (clonal) hematologic disorder, involving hematopoietic stem cells and characterized by the presence of primitive or atypical myeloid or lymphoid cells in the bone marrow and the blood. "The transporter is frequently expressed on malignant hematopoietic and lymphoid cells, and evolving literature associates ABCG2 single nucleotide polymorphisms (SNPs) not only with anti-cancer drug efficacy, but also with incidence of leukaemia." (PMID 28880238, 2017). "In the subgroup analysis by cancer types, the ABCG2 C421A genotype significantly reduced the risk of leukemia and other cancers in additive model (OR = 0.741, 95%CI = 0.577-0.951; OR = 0.669, 95%CI = 0.511-0.876)." (PMID 22937733, 2012). "Moreover, the overexpression of ABCG2 in leukemia cells is associated with poor clinical outcomes, including reduced complete remission rates and overall survival." (PMID 41378310, 2025). "Moreover, the study of complex molecular pathways involved in ABCG2 expression has underlined that many of them are also involved in cancer/leukemia pathogenesis." (PMID 38255216, 2024). "Its downstream targets include anti-apoptotic proteins such as Bcl-2, and MDK also facilitates drug efflux by upregulating ABC transporters, such as MDR1 and ABCG2, leading to multidrug resistance in gastric, leukemia, and ovarian cancer models." (PMID 40500394, 2025). "As another example, imatinib was identified as a substrate of ABCG2 in treating leukemia, and ABCG2 was found to be upregulated in imatinib-resistant leukemia cells." (PMID 39114355, 2024). "This work highlights that most mechanisms affecting ABCG2 expression are also involved in leukemia pathogenesis." (PMID 37108308, 2023). "Overexpression of some members of this family, including P-glycoprotein (MDR1) and breast cancer resistance protein (ABCG2), have been implicated in leukemia stem cell drug resistance." (PMID 35057108, 2022). "A similar observation was made in leukemia cells, where inhibition of miR-212 led to increased expression of ABCG2 and imanitib resistance." (PMID 35628654, 2022). "For example, the resistance to imatinib in the human leukemia cell line (K562) was proportional to the expression level of ABCG2." (PMID 34572902, 2021). "In order to find a suitable ABCG2 (ATP-binding cassette sub-family G member 2) transporter substrate, virtual screening was performed among a list of drugs used in leukemia and PLD was selected." (PMID 34149737, 2021). "Afatinib was first found to suppress ATP-binding cassette subfamily G member 2 (ABCG2) activity, self-renewal capacity, and tumorigenesis in patient-derived leukemia cells—specifically, via ABCG2 promoter methylation." (PMID 34680249, 2021). "To investigate the function of MMP9 and ABCG2 in human leukemia cells, we overexpressed these two genes in the NB4 cells." (PMID 34093860, 2021). "The overexpression of ABCG2 has been reported in leukemia and in solid tumors, such as NSCLC and liver cancer." (PMID 31940916, 2020). "Multidrug binding and transport by the ATP-binding cassette transporter ABCG2 is a factor in the clinical resistance to chemotherapy in leukaemia, and a contributory factor to the pharmacokinetic profiles of many other prescribed drugs." (PMID 29661915, 2018). "Recently, tricetin was identified as a novel flavonoid ABCG2 inhibitor, but the effect of tricetin on the stemness of leukemia should be further investigated." (PMID 28758971, 2017). "From these research databases, we selected four genes of interest, FLT-3, WT1, Bmi-1, and ABCG2, known as oncogenic and stem cell regulators that participate in leukemia initiation and progression." (PMID 26847520, 2016). "Thereby, we evaluated the endogenous levels of PTEN, PI3K, p-PI3K, p-Akt and ABCG2 in four leukemia cell lines." (PMID 24603487, 2014). "Next, we evaluated the effect of ABCG2 overexpression on the mitoxantrone-induced cell cycle changes in leukemia cell lines." (PMID 24603487, 2014).